PRDX1 (peroxiredoxin 1)
Diseases named in the same sentence as PRDX1 in open-access papers (continued):
Sharing a sentence is not in itself a finding about the gene and the disease.
tumor (continued). "This study shows the upregulation of PRDX1 and PRDX2 antioxidant enzymes in GBM compared to non-tumor brain tissues." (PMID 37566013, 2023). "PRDX1 is a safeguard for the activity of PTEN and is essential for the tumor suppressive functions of PTEN." (PMID 37198696, 2023). "According to the GO results, catalase (CAT), peroxiredoxin-1 (PRDX1), and PRDX4 were related to hydrogen peroxide catabolic process and reactive oxygen species metabolic process, which led to tumor cell apoptosis." (PMID 37124724, 2023). "Obviously, for the expression level, PRDX1 was strongly expressed in normal tissues, but GPX2 was moderately expressed in tumor tissues." (PMID 35705729, 2022). "For one thing, in the PRDX1/5-low group, a high level of ROS can induce the production of chemokines (for example, CXCL9), thereby recruiting T cells into the tumor." (PMID 35350568, 2022). "PRDX1 inhibits the activation of oncogenes (c-Abl and c-myc, and PTEN) which is essential for its tumor-suppressive function." (PMID 35812179, 2022). "Formalin-fixed, paraffin-embedded (FFPE) tissue from 119 cases of urothelial cancer and 5 cases with normal mucosa was used to evaluate the expression and localization of the protein (PRDX1 and PRDX2) in the tumor by immunohistochemistry." (PMID 35812179, 2022). "Subsequently, the correlations between PRDXs and immune subtypes, tumor stemness demonstrated that PRDX1, PRDX4, PRDX6 were closely related with type C1, C2 and C6 infiltrates, while tumor stemness scores were positively with all PRDX members." (PMID 34246267, 2021). "Correlations between higher levels of PRDX1, PRDX4, PRDX6 and type 1, 2, and 6 infiltrates (C1, C2 and C6), suggesting the tumor promoting effect of these PRDXs." (PMID 34246267, 2021). "The results demonstrated that PRDX1, PRDX4, PRDX5 and PRDX6 were significant difference between tumor and normal tissues, which were also validated in HPA database." (PMID 34246267, 2021). "On the other hand, low expression levels of PRDX1, PRDX4 and PRDX6 were correlated with C3 subtypes, indicating that they are potential tumor promoters, similar to pan-cancer results." (PMID 34246267, 2021). "M2-like macrophage activation, immunosuppressive tumor microenvironment, and tumor growth were reversed by inhibiting LAMP2A, whose targets were found to be peroxiredoxin 1 (PRDX1) and CREB-regulated transcription coactivator 1 (CRTC1)." (PMID 33990205, 2021). "Stimulating the ESCC cells with the Aurora A inhibitor Tripolin A reversed the effect of the over-expressed Prdx1 on p-Aurora A and HDAC6 proteins, and decreased p-Aurora A enhancement of cilium regeneration and inhibited the invasion of tumor cells." (PMID 32357862, 2020). "Inhibiting Prdx1 expression with the shPrdx1 lentivirus promoted cilia formation in EC9706 cells and inhibited the invasion capacity of the tumor cells." (PMID 32357862, 2020). "Cell and animal experiments demonstrated that Prdx1 plays a role in regulation of the critical NEDD9-Aurora A-HDAC6 signal axis of cilium disaggregation and influences the tumor formation and invasion capacity of ESCC cells." (PMID 32357862, 2020). "We previously found that Prdx1 can promote cilia disaggregation in ESCC and strengthen the invasion capacity of tumor cells." (PMID 32357862, 2020). "We subsequently investigated expression of PRDX1, FMNL, NCL, CLIC3, FLNA, PHB2, and FABP5 of 229 ESCC tumor tissues by TMA." (PMID 29683265, 2018). "However, PRDX1 gene mutations have not been identified in human tumours." (PMID 27653015, 2017). "We found that PRDX1 and PRDX2 are upregulated in tumor B cells as compared with normal counterparts." (PMID 26636537, 2016). "To extend these observations, we analyzed the expression of PRDX1 and PRDX2 in a panel of B cell-derived tumor cell lines." (PMID 26636537, 2016). "Several proteins were identified as significantly elevated in abundance in tumor TIF, including peroxiredoxin 1 (PRDX1)." (PMID 23914992, 2013).
tumor (continued). "Of these, PRDX1 was selected for validation in TIF by Western blot and expression of PRDX1 was confirmed to be upregulated in tumor TIF." (PMID 23914992, 2013). "Among the identified five distinct macrophage subpopulations (FCN1+Inflam-Mac, PRDX1+LA-Mac, HERPUD1+LA-Mac, ALOX5AP+LA-Mac and OxP-Mac), OxP-Mac predominantly enriched in normal kidney tissues, whereas the other subtypes were mainly found in tumor regions." (PMID 41601657, 2026). "Functional polarization analysis showed these macrophage sub types were not canonical M1/M2 features, while tumor-enriched PRDX1+ and HERPUD1+LA-Mac exhibited mixed M1/M2 features." (PMID 41601657, 2026). "Moreover, we found that PRDX1 was negatively correlated with the immune infiltration of dendritic cells (DCs) in the tumor microenvironment (TME) of LUAD, further suggesting an oncogenic role of PRDX1." (PMID 40303499, 2025). "Furthermore, endogenous ligands like Peroxiredoxin-1 can activate TLR4, stimulating tumor angiogenesis and expansion in murine models, solidifying the role of TLR4-mediated inflammation in PCa pathogenesis." (PMID 41162970, 2025). "Excessive ROS production by T15 treatment activates different counter mechanisms trying to partially protect the tumor cells against oxidative stress, such as the higher expression of NOX1 on MCF7 cells; PARK7, PRDX1 and PRDX3 on MDA-MB231 cells; and UCP1 elevation in PANC1 cells." (PMID 41011284, 2025). "Moreover, circZNF215 competitively binds to PRDX1, inhibiting the interaction between PRDX1 and PTEN, thereby reducing the activity of the PTEN/AKT signaling pathway and promoting tumor metastasis as well as ipatasertib resistance." (PMID 39584047, 2024). "Degradation of LAMP2a, PRDX1, and CRTC1 to promote pro-tumor activation of macrophages." (PMID 38370407, 2024). "Intriguingly, the EVs secreted by invasive tumoroids (3D d10‐d14) contained several unique proteins promoting tumour growth and invasion, for example, SLC4A7, SLC12A2, FABP5, PRDX1, CD59 and CD73, showing that specific oncogenic signals are loaded in EVs upon invasion." (PMID 38938900, 2023). "High expression of PRDX1 in HCC tissues corresponds to adverse clinical outcomes, and the mechanism may be related to promoting tumor angiogenesis and regulating cell migration and invasion 43-45." (PMID 35371321, 2022). "Moreover, the promoter activities of GCLC, GSR, PRDX1, and MSRA were significantly elevated in HFD tumor cells compared to LFD cells." (PMID 35182054, 2022). "Second, previous studies revealed that PRDX1 excessive expression enhances epithelial-mesenchymal transition (EMT) by inducing transforming growth factor beta 1; EMT is regarded as a critical process in tumor invasion and metastasis." (PMID 33747258, 2021). "Furthermore, the mRNA expression levels of PRDX1, PRDX4 and PRDX6 were closely related with tumor stage of BLCA." (PMID 34246267, 2021). "The up-regulation of PRDX2, down-regulation of PRDX6, and the nuclear absence of PRDX1 in COAD tumor cells were indicated." (PMID 32231717, 2020). "Our study showed that PRDX1 abundantly expressed in tumor tissues but not in corresponding para-carcinoma tissues." (PMID 31956363, 2020). "Mice lacking the peroxiredoxin Prdx1 exhibit an increased incidence of tumor formation, whereas baker’s yeast (Saccharomyces cerevisiae) lacking the orthologous peroxiredoxin Tsa1 exhibit a mutator phenotype." (PMID 30486489, 2018). "PRDX1 protein expression correlated with smaller tumor size (P = 0.011), low tumor grade (P = 0.002), negative Ki67 status (P = 0.004) and lobular subtype (P = 0.003), whilst there was a borderline significant correlation with positive ER status (P = 0.05)." (PMID 25011585, 2014). "It was found that Prdx1 was overexpressed in ESCC tissues when compared to adjacent normal tissues, and the expression level of this protein was also elevated in other types of tumor tissues." (PMID 24009050, 2013).
tumor (continued). "One study demonstrated that Prdx1 inhibits the activation of oncogenes such as c-Abl and c-myc, and it can also be considered as a safeguard for the lipid phosphatase activity of PTEN, which is essential for its tumor-suppressive function." (PMID 24009050, 2013). "Prdx1 contribute to the inhibition of tumorigenesis through PTEN/Akt pathway and its lower expression in the tumor indicated high tumor proliferation, increased metastasis and could be used as cancer biomarker." (PMID 21933383, 2011). "TIMER2.0 analysis showed that overexpression of PRDX1 was negatively correlated with infiltration of CD4+ and CD8+ T cells, while positively correlated with infiltration of M2 macrophages in CRC, suggesting a potential role for PRDX1 in shaping anti‐tumor immunity via macrophage polarization." (PMID 41306557, 2025). "Moreover, PRDX1 may play an important role in modulating EGFR-TKI therapeutic sensitivity and tumor immunity, highlighting its promise as a therapeutic target to improve clinical outcomes in LUAD." (PMID 40303499, 2025). "Moreover, PoD exhibited no significantinhibitory effect on tumor proliferation in the PRDX1-KD 4T1 mousemodel." (PMID 40028362, 2025). "Thus, we validated the correlation between PRDX1 and EGFR-TKI sensitivity through a series of in vitro experiments and found that PRDX1 inhibition along with osimertinib treatment resulted in synergistic inhibition of tumor growth." (PMID 40303499, 2025). "In contrast, the tumor sensitivityof PoD on PRDX1-OV 4T1 tumors was increased.These results further demonstrated that PRDX1 could influence cellgrowth in vivo and that the antitumor effect of PoDon TNBC cells in vivo is PRDX1-dependent." (PMID 40028362, 2025). "PRDX1 was overexpressed (mRNA) while nuclear absent (protein) in the tumor tissues." (PMID 32231717, 2020). "Thus, Prdx1 and primary cilia may play an important role in the development of ESCC, making Prdx1 an exciting potential target for tumor treatment." (PMID 32357862, 2020). "Importantly, the levels of PRDX1 mRNA and protein were dramatically increased in primary tumor tissues (PTs) than in corresponding adjacent non-tumor tissues (ANTs)." (PMID 29492195, 2018). "Supernatant from tumor cells in which Prdx1 was knocked down could not induce this secretion." (PMID 35052630, 2022). "However, the nuclear absence of PRDX1 in COAD tumor cells was consistent." (PMID 32231717, 2020). "There was no significant change in the protein expression of PRDX1, PRDX2 and CD20 (a DLBCL tumor cell marker) in either the control group or the ART group." (PMID 40645965, 2025). "Western blotting from the tumor tissue corroborated these observations, showing diminished GPX4 levels without alterations in PRDX1 and PRDX2 expressions." (PMID 40645965, 2025). "PRDX1 and PRDX2 were both found to be expressed in tumor cells and these proteins were absent in normal mucosa evaluated as control." (PMID 35812179, 2022). "The antioxidant genes NQO1, GSTP1, PRDX1 and NQO1 were upregulated specifically in detached cells, indicating that antioxidant mechanisms were not fully capable of protecting tumor cells against the PDT-inflicted oxidative injuries." (PMID 34371724, 2021). "These newly explored roles of Prdx1 are independent of its peroxide-detoxifying function, consistent with our findings that Prdx1 suppresses JNK1 activation by forming Prdx1-GSTπ-JNK1 heterotrimeric complexes during ECM detachment of tumor cells." (PMID 35027562, 2022). "It is worth noting that mRNA expression levels of other antioxidative enzymes, namely peroxiredoxin 1 (Prdx1), glutathione peroxidase (Gpx), but not superoxide dismutase 1 (Sod1), were similarly higher in the PMA type of tumor tissue than in healthy parotid tissue." (PMID 34360635, 2021).
cancer (121 papers, 2007 to 2025). A tumor composed of atypical neoplastic, often pleomorphic cells that invade other tissues. "Peroxiredoxin 1 (PRDX1), a redox-regulating antioxidant enzyme, has been implicated in various cancer-related processes." (PMID 40693141, 2025). "PRDX1’s role in various cancers is mainly associated with its antioxidant activity and immune regulation." (PMID 40256656, 2025). "Gene set enrichment analysis (GSEA) demonstrated a positive correlation between high PRDX1 expression and pathways associated with the cell cycle, cancer, and drug resistance, including DNA synthesis, MYC targets, and ATP-binding cassette(ABC) transporters." (PMID 40825764, 2025). "All six PRDXs (PRDX1-6) are implicated in tumorigenesis and disease progression in diverse cancers, although antitumor functions have also been reported." (PMID 38254783, 2024). "Although Prdx1 has been implicated in cancer cell proliferation, metastasis, invasion, angiogenesis, and other processes, the underlying molecular mechanisms remain incompletely understood." (PMID 38007535, 2023). "On one hand, it is overexpressed in some malignant tumors, but on the other hand, PRDX1‐deficient mice are prone to develop cancers." (PMID 37259925, 2023). "The mutation frequency, mutation type, and copy number alterations (CNA) of PRDX1 in pan-cancer were also investigated." (PMID 37781072, 2023). "Whereas the endothelial cells and cancer associated fibroblasts were more abundant in the poor prognosis PRDX1 high expressing HCC patient population." (PMID 37842089, 2023). "Loss of peroxiredoxin 1 (PRDX1) activates fibroblasts to become invasive cancer-associated fibroblasts (CAFs) by regulation of c-Jun N-terminal kinases/JNK signaling, and promotes cancer development in mammary gland." (PMID 36500393, 2022). "Cancer-associated protein alterations such as upregulation of peroxiredoxin-1, annexin 5, and iNOS, and downregulation of RDH12, retinaldehyde dehydrogenase 1, SOD1, and MYL 9, were found in the EC tissues of the diabetic group." (PMID 35454982, 2022). "An increase in reactive oxygen species (ROS) is not only a hallmark of cancer cells but also the leading driving force for PRDX1 oligomerization." (PMID 33712558, 2021). "PRDX1 knockout mice acquire severe hemolytic anemia and are more susceptible to the development of several cancers." (PMID 31956363, 2020). "This seems to be inconsistent with our findings that low PRDX1 expression was associated with poor OS, but double effects of PRDXs on cancer cells have been identified previously." (PMID 32382548, 2020). "A number of studies have addressed the association between PRDX1 expression and prognosis in several types of human cancers; however, the results are inconsistent and inconclusive." (PMID 30104402, 2018). "These independent observations reinforce the notion that PRDX1 is important to suppress the pathogenesis of inflammation-associated cancers such as colorectal and gastric and prolong the survival of the patients." (PMID 27388124, 2016). "Furthermore, high PRDX1 expression was associated with the increased expression of ROS-related genes, aligning with the observation that cancer cells typically exhibit elevated ROS levels accompanied by enhanced antioxidant activity." (PMID 40825764, 2025). "Additionally, elevated nuclear ROS levels in primary tissues isolated from another Prdx1-knockout mouse model resulted in increased DNA damage and heightened cancer susceptibility." (PMID 39720522, 2024). "Our findings strongly suggest that high expression levels of GLUT3 or functionally inactive PRDX1 or both will cause cells to be hypersensitive to arsenite and may serve to identify cancer patients who could benefit from arsenite therapy." (PMID 38067110, 2023).
cancer (continued). "Alterations in the proteins that are usually associated with cancer, including the upregulation of peroxiredoxin-1, annexin 5, and iNOS, and down-regulation of RDH12, retinaldehyde dehydrogenase 1, SOD1, and MYL 9, were found in the EC tissues of the diabetic group." (PMID 35454982, 2022). "PRDX1 overexpression is associated with poor outcomes of cancers and may serve as a prognostic biomarker for malignant patients." (PMID 33747258, 2021). "We next examined whether loss of PRDX1 in mammary fibroblasts (MF) led to phenotypic characteristics that resemble cancer-associated fibroblasts (CAFs)." (PMID 31419957, 2019). "PRDX1 is a major 2-Cys member of the peroxiredoxin family that plays important roles in cell proliferation, differentiation, and apoptosis under stress conditions and is associated with poor prognosis in cancers." (PMID 31429766, 2019). "We next checked whether PRDX1 mRNA expression level would correlate with inflammation-associated cancers." (PMID 27388124, 2016). "Notably, the primary alteration in PRDX1 within these cancers is the presence of genetic mutations." (PMID 37781072, 2023). "Therefore, the controversial role of PRDX1 in cancer metabolism might also be linked with its regulation of aspartate metabolism." (PMID 37259925, 2023). "Moreover, PRDX1 deficiency not only induced oxidative stress and impaired macrophage lipophagic flux but also decreased autophagy by attenuating NF-KB activation in cancer cells." (PMID 36364745, 2022). "Thus, the association between LINC00460 and PRDX1 may be a biomarker for accurate prognosis and a potential target for cancer therapy in the context of HNSCC." (PMID 31429766, 2019). "Therefore, Prdx1 oligomerization may be differentially regulated in normal and cancer cells and associated with changes in Kras effector phosphorylation." (PMID 29190947, 2017). "The molecular chaperone activity of PRDX1 has attracted significant attention for its role in cancer growth and drug resistance." (PMID 41306557, 2025). "In summary, we have identified a potential PRDX1 inhibitor that warrants further investigation for the treatment of cancer." (PMID 40771925, 2025). "PRDX1 was found to be overexpressed in AML, and its expression correlated with poor prognosis and the activation of AML- and cancer-associated pathways." (PMID 40825764, 2025). "Clusters 3 and 5 showed elevated expression of genes associated with cancer development and progression, such as CEBPB, PLIN2, PRDX1, PSMD6, and TXNRD1." (PMID 39805002, 2025). "It is well established that PRDX1-deleted cancer cell lines accumulate high levels of reactive oxygen species (ROS), which have the propensity to oxidize proteins, as well as create oxidative DNA lesions." (PMID 40387816, 2025). "Elevated PRDX1 expression has been observed in several human tumors, including lung, breast, liver, colon and other cancers." (PMID 40771925, 2025). "PRDX1 plays distinct roles in tumorigenesis, acting as both a promoter and a suppressor depending on the cancer type." (PMID 40825764, 2025). "In conclusion, PRDX1 can be significantly involved in the process of cancer progression through enzymatic activity as well as interactions with other factors in addition to enzymatic activity." (PMID 39234629, 2024). "have demonstrated that Prdx1-knockout mice, while viable and fertile, develop severe hemolytic anemia and exhibit an increased incidence of malignant cancers." (PMID 39720522, 2024). "The second subnetwork containing 13 nodes and 12 edges showed the interaction between PRDX2 and TAGLN2 as well as a mild increase in multiple components of the peroxisome (SOD1, CAT, PRDX5, PRDX1) and proteoglycans in cancer (FLNA, STAT3)." (PMID 38322285, 2023). "Anti-apoptotic activity of PRDX1 reduces the intracellular accumulation of ROS that plays a pivotal role in the progression and invasion of various cancers." (PMID 37501157, 2023).